ZNF334 (zinc finger protein 334)
Description:
May be involved in transcriptional regulation.
Synonyms: bA179N14.1
Tractability: PROTAC: ubiquitination databases record sites on it.
Gene: Protein-coding gene on chromosome 20 (46,499,630 to 46,513,596, reverse strand). Ensembl gene ENSG00000198185.
Subcellular location: Nucleus
Subcellular location (Human Protein Atlas): Nucleoplasm; Cytosol
Pathways (Reactome):
Gene expression (Transcription): Generic Transcription Pathway
Gene Ontology:
Molecular function: protein binding; DNA-binding transcription factor activity, RNA polymerase II-specific; RNA polymerase II cis-regulatory region sequence-specific DNA binding
Biological process: regulation of transcription by RNA polymerase II; regulation of DNA-templated transcription
Cellular component: nucleus; nuclear lumen
Genetic constraint (gnomAD): Loss-of-function variants: 10 observed, 10.77 expected, observed/expected ratio (o/e) 0.93, 90% interval 0.57 to 1.56. The upper end of that interval is the gene's LOEUF score, 1.56, which puts it in group 6 of 6, group 1 being the genes least tolerant of losing a copy. Missense variants: 792 observed, 841.15 expected, observed/expected ratio (o/e) 0.94, 90% interval 0.89 to 1. Synonymous variants: 272 observed, 284.56 expected, observed/expected ratio (o/e) 0.96, 90% interval 0.87 to 1.06.
Homologues: Orthologues: macaque ZNF334 (97% identical), chimpanzee ZNF334 (94% identical), rat Zfp334 (71% identical), mouse Zfp334 (70% identical). Paralogues in human: ZNF658 (47% identical), ZNF33B (46% identical), ZNF717 (44% identical), ZNF182 (44% identical), ZNF484 (43% identical), ZNF41 (41% identical), ZNF33A (41% identical), ZNF605 (41% identical), ZNF12 (40% identical), ZNF300 (40% identical), ZNF568 (40% identical), ZNF782 (40% identical), and 164 more.
Diseases named in the same sentence as ZNF334 in open-access papers:
ZNF334 is named in the same sentence as 22 diseases in open-access papers, as found by Europe PMC text mining. Sharing a sentence is not in itself a finding about the gene and the disease. The quoted sentences say what the papers report.
colorectal cancer (3 papers, 2023 to 2025). A primary or metastatic malignant neoplasm that affects the colon or rectum. "Aberrant DNA methylation, a hallmark of colorectal cancer development, was found to affect ZNF334, with TET1 identified as a key regulator of this process." (PMID 40520993, 2025). "Their experiments, conducted both in vitro and in vivo, demonstrated that this approach successfully restored ZNF334 expression, leading to the suppression of colorectal cancer growth." (PMID 40520993, 2025).
hepatocellular carcinoma (3 papers, 2022 to 2024). A malignant tumor that arises from hepatocytes. "In addition, it has been found that ZNF334 expression is downregulated in malignant tissues, and its expression is inversely correlated with clinical outcome of patients with various cancers, including hepatocellular carcinoma (HCC) and triple-negative breast cancer (TNBC)." (PMID 36966142, 2023).
liver cancer (2 papers, 2022 to 2024). An epithelial or non-epithelial malignant neoplasm that arises from the liver. "Cox univariate analysis found that ZNF334, AFP, AST, and MVI were related to overall survival (OS) in patients with liver cancer; ZNF334, AFP, MVI, and portal vein tumor thrombus were related to postoperative relapse-free survival (RFS)." (PMID 35534462, 2022). "For tissues from patients, the expression of ZNF334 at mRNA level in the tumor tissues significantly decreased by detecting the cancer and adjacent tissues of 213 liver cancer patients." (PMID 35534462, 2022). "In order to further investigate the relationship between ZNF334 and the prognosis of liver cancer patients, we collected the tumor tissues from 213 liver cancer patients and detected the expression of ZNF334 at the mRNA level." (PMID 35534462, 2022). "In addition, combined with clinical samples and follow-up data, we found that compared with paracancerous tissues, the expression of ZNF334 in tumor tissues of liver cancer patients was significantly reduced." (PMID 35534462, 2022).
lung squamous cell carcinoma (2 papers, 2024 to 2025). "ZNF334 is a highly generalizable gene to lymph node metastasis of lung squamous cell carcinoma and its expression alter certainly under senescence conditions." (PMID 38637790, 2024).
rheumatoid arthritis (2 papers, 2023 to 2025). A chronic, systemic autoimmune disorder characterized by inflammation in the synovial membranes and articular surfaces. "Previous studies described reduced ZNF334 transcription levels in cancer tissues and in CD4 + T cells of rheumatoid arthritis." (PMID 41168503, 2025). "Downregulation of ZNF334 expression has been reported in various cancer tissues and in the CD4 + T cells of patients with rheumatoid arthritis." (PMID 41168503, 2025). "ZNF334, a newly identified member of ZNFs, was initially identified as a molecular marker involved in rheumatoid arthritis (RA) and was extremely reduced in CD4 lymphocytes of RA." (PMID 36966142, 2023).
Arthralgia (1 paper, 2025). "Given that abrupt reductions in temperature have been reported to trigger arthralgia in patients with JIA, we analyzed the gene expression signature of ZNF334 in an RNA-seq dataset (E-MTAB-14035) derived from classical monocytes of patients with JIA and controls." (PMID 41168503, 2025).
colon cancer (1 paper, 2025). "Indeed, 6 out of 10 leading TFs have direct evidence and some experimental validation of their involvement in colon cancer risk and progression: ZNF334, FOXD2, FOXD3, POU3F3, NR1H4, and VSX2." (PMID 41114645, 2025).
juvenile idiopathic arthritis (1 paper, 2025). Juvenile idiopathic arthritis (JIA) is the term used to describe a group of inflammatory articular disorders of unknown cause that begin before the age of 16 and last over 6 weeks. "Next, we examined whether the ZNF334 loss-of-function expression signature identified through RNA-seq analysis is present in monocytes derived from patients with other chronic inflammatory diseases, such as juvenile idiopathic arthritis (JIA)." (PMID 41168503, 2025).
lung carcinoma (1 paper, 2025). "Integrating such emerging evidence broadens the molecular landscape of lung cancer progression and reinforces the need to evaluate distinct gene signatures—including PECAM1 and ZNF334—across different histological contexts to optimize biomarker-guided strategies for early detection and treatment." (PMID 40361912, 2025).
progressive sensorineural hearing loss (1 paper, 2025). "We identified a ZNF334 truncation mutation (p.Thr399fs) in a rare case of late-onset cold-induced autoinflammatory disease with elevated TNF-α, IL-1β, IL-6, and extracellular heat shock protein 90 (eHsp90) plasma levels and progressive sensorineural hearing loss." (PMID 41168503, 2025).
tumor (5 papers, 2021 to 2025). "C2H2-type ZnF proteins have been reported to primarily function as transcription factors, and ZNF334 has been described as a tumor-suppressor gene targeting signaling pathways involving tumor growth and metastasis." (PMID 41168503, 2025). "Our results indicated that the targeted demethylation of ZNF334 significantly reduced the tumor volume of HCT116 cells (tumor volume: sgRNA: 514.7 ± 208.8 mm3 versus sgZNF334: 242.6 ± 90.8 mm3)." (PMID 36966142, 2023). "We also determined the effect of the targeted demethylation of ZNF334 on tumor vascularization by staining for endothelial-specific antigen CD31." (PMID 36966142, 2023). "Collectively, these data imply that the targeted demethylation of ZNF334 is a potential anti-tumor strategy for the treatment of CRC." (PMID 36966142, 2023). "Firstly, we compared the expression of ZNF334 between 24 tumor and normal tissues using Pan-cancer view profiling datasets collected in the TCGA project." (PMID 36966142, 2023). "The results showed that ZNF334 expression was decreased in most tumor tissues compared with normal tissues, and there was a significant difference in the downregulation of ZNF334 expression in CRC tissues (p < 0.05)." (PMID 36966142, 2023). "We further evaluated the effects of different expression levels of ZNF334 on the tumor formation ability of HCC cell lines." (PMID 35534462, 2022). "Twelve patients’ samples were used to examine the ZNF334 protein level, which showed a descending trend in tumor tissues compared to the paratumor tissues." (PMID 35534462, 2022). "Furthermore, given the reported associations of ZNF334, Hsp90 and TRPM8 with tumor progressions, and the potential of cancer hyperthermia therapies, this study also provides hints in thermal modulation of tumor stress responses." (PMID 41168503, 2025). "Cox multivariate analysis found that AFP > 400 ng/ml, low ZNF334 expression and MVI were independent risk factors that affected the patients’ OS; while AFP > 400 ng/ml, low ZNF334 expression and portal vein tumor thrombus were the independent risk factors that affected patients’ RFS." (PMID 35534462, 2022). "The area under the curve was 0.68 for ZNF334 and 0.88 for TINAGL1 between lung SCC samples and lung non-tumor samples." (PMID 38637790, 2024). "ZNF334 (p value < 0.0001) and TINAGL1 (p value < 0.0001) mRNA expression revealed a marked decrease in the lung of SCC tumor-bearing C57BL/6J compared to normal lung tissue and placebo-controlled." (PMID 38637790, 2024). "Targeted demethylation of ZNF334 also dramatically inhibited the weight of HCT116 cells (tumor weight: sgRNA: 1.053 ± 0.069 g versus sgZNF334: 0.495 ± 0.029 g)." (PMID 36966142, 2023). "Compared with the ZNF334 high expression group, the proportion of people with high serum AFP( > 400 ng/ml), tumor number and portal vein tumor thrombus was greater, while the proportion of people with tumor capsule was lower." (PMID 35534462, 2022). "On the other hand, fewer subcutaneous tumors were formed in the mice with ZNF334-OE injected, and even no tumor formed at 1 × 105 concentration." (PMID 35534462, 2022). "Chi-square showed that ZNF334 was related to tumor growth-related indicators-alpha-fetoprotein (AFP), number of tumors and tumor capsule, and was also concerned with metastasis-related indicators-portal vein tumor thrombus." (PMID 35534462, 2022). "Further measuring the markers related to the tumor formation ability in mice subcutaneous tumors, we found that EpCAM, CD13, CD24, CD44, CD90 and CD133 in ZNF334-OE cells was significantly lower than that of the control group, which was consistent to the phenotype of the mice model." (PMID 35534462, 2022).
tumor (continued). "However, the expression of ZNF334 in CRC and its regulatory effect on tumor proliferation and apoptosis remain unclear." (PMID 36966142, 2023).
cancer (4 papers, 2022 to 2025). A tumor composed of atypical neoplastic, often pleomorphic cells that invade other tissues. "The results manifested that the methylation degree of ZNF334 promoter region in cancer tissues was significantly higher than that in adjacent tissues of the same patient." (PMID 35534462, 2022). "We further analyzed the expression of ZNF334 in CRC based on individual cancer stages." (PMID 36966142, 2023).
lung (1 paper, 2024). "We next examined the expression of ZNF334 and TINAGL1 genes in lung specimens from C57BL/6J mice with LNM lung SCC tumorous lesions." (PMID 38637790, 2024).
ZNF334 also shares sentences with these, for which no sentence is quoted: allergic reaction (1 paper); benign tumors (1); breast carcinoma (1); infection (1); metastatic cancers (1); polyarticular JIA (1); rheumatic disease (1); skin rashes (1); urticaria (1).